ASS1 (argininosuccinate synthase 1)
Diseases named in the same sentence as ASS1 in open-access papers (continued):
Sharing a sentence is not in itself a finding about the gene and the disease.
citrullinemia type I (45 papers, 2012 to 2026). "Sequence variants in the urea cycle gene argininosuccinate synthase (ASS1) cause Citrullinemia type 1 (CTLN1), a rare autosomal recessive disease." (PMID 42308225, 2026). "We chose two clinically relevant, pathogenic mutations in TTR (Thr80Ala) and ASS1 (frameshift at the Phe150, “Phe150fs”) genes, causing hereditary amyloid transthyretin and type I citrullinemia, respectively." (PMID 40498069, 2025). "Citrullinemia type I (CTLN1) is an autosomal recessive disorder caused by variants in the arginine succinate synthase gene (ASS1)." (PMID 40837674, 2025). "The survey returned two rare pathogenic coding mutations leading to citrullinemia type I: rs148918985, p.Arg265Cys, C>T; and rs121908641, p.Gly390Arg, G>A in the argininosuccinate synthase 1 (ASS1) gene." (PMID 38927689, 2024). "Firstly, expanding the sample size of citrullinemia type 1 patients is necessary to further validate the effectiveness of PGT methods in preventing the transmission of ASS1 gene mutations." (PMID 39175751, 2024). "The study identified previously unreported variations in the ASS1 gene causing citrullinemia type 1." (PMID 39175751, 2024). "Mutations in ASS1 can cause citrullinemia type 1, and functional tests showed that mutation in ASS1 affects its expression." (PMID 39175751, 2024). "Individuals with germline pathogenic variants in the gene encoding ASS1 have citrullinemia type I (CTLN-I)." (PMID 38858597, 2024). "In this research, we present a family case of citrullinemia type 1 involving previously unreported mutation sites in ASS1, classified as pathogenic or likely pathogenic according to ACMG guidelines." (PMID 39175751, 2024). "Citrullinemia type I (CTLN1) is a rare autosomal recessive disorder caused by mutations in the gene encoding argininosuccinate synthetase 1 (ASS1) that catalyzes the third step of the urea cycle." (PMID 36499263, 2022). "In the present study, we performed genetic analysis of nine Chinese infants with citrullinemia, and identified homozygous or compound heterozygous mutations of ASS1 and SLC25A13." (PMID 35309121, 2022). "Citrullinemia type 1 is an autosomal recessive metabolic disease caused by ASS1 gene mutations encoding argininosuccinic acid synthetase enzyme which is within the pathway of arginine and nitric oxide biosynthesis." (PMID 35433176, 2022). "Citrullinemia type I (CTLN1) is a UCD caused by decreased activity of argininosuccinate synthase 1, a critical urea cycle enzyme." (PMID 36536326, 2022). "A previous study showed that PRMT7 interacts with ASS1, and that several mutations associated with citrullinemia disrupt this interaction." (PMID 35309121, 2022). "Citrullinemia type 1 (CTLN1), or argininosuccinate synthetase (ASS) deficiency, is a rare autosomal recessive metabolic disorder caused by mutations in the ASS1 gene." (PMID 35433176, 2022). "ASS-1-mutated HLSCs were obtained from a small biopsy of the discarded liver from a transplanted patient with citrullinemia type I. The mutated HLSCs were characterized by cytofluorimetric analysis to confirm typical HLSC markers." (PMID 33981703, 2021). "Deficiency of ASS1 in patients leads to citrullinemia, an autosomal recessive urea cycle disorder characterized with marked plasma citrulline increase and punctuated hyperammonemia." (PMID 33859183, 2021). "A mutation in the ASS1 gene is associated with citrullinemia, which is an autosomal recessive urea cycle disorder that causes ammonia to accumulate in the blood causing lethal reaction in newly-born Holstein Friesian calves." (PMID 33806889, 2021). "ASS1 genetic deficiency in patients leads to an autosomal recessive urea cycle disorder citrullinemia, while its somatic silence or down-regulation is very common in various human cancers." (PMID 33859183, 2021). "Recently, iPSCs derived from Citrullinemia type I patients with homozygous G390R mutations in the ASS1 gene have been used to develop a disease-specific model." (PMID 31921856, 2019).
citrullinemia type I (continued). "In seven couples, citrullinemia type 1 was suspected based on elevated plasma citrulline in index patient and these couples were only tested for mutations in ASS1 gene." (PMID 30285816, 2018). "Mutations in the ASS1 gene cause citrullinemia type I, a rare autosomal recessive disorder characterized by neonatal hyperammonemia, elevated citrulline levels, and early neonatal death." (PMID 28750687, 2017). "Citrullinemia type I is an inherited disorder of the urea cycle caused by a genetic mutation in the ASS1 gene." (PMID 28750687, 2017). "Citrullinemia type I is an autosomal recessive disorder caused by a deficiency in argininosuccinate synthase (ASS; common gene symbol alias: ASS1), an enzyme that catalyzes the third reaction of the urea cycle." (PMID 28750687, 2017). "Regarding type 1 citrullinemia, twelve different mutations in the ASS1 gene were identified in 14 subjects." (PMID 25433810, 2014). "Citrullinemia is a rare recessive urea cycle disorder due to mutations in the ASS1 (type I citrullinemia) gene which cause deficiency of arginosuccinate synthetase enzyme, necessary for catalyzing the formation of arginosuccinic acid from citrulline and aspartic acid." (PMID 37008993, 2023). "Genetic ASS1 deficiency causes a urea cycle disorder citrullinemia." (PMID 33859183, 2021). "Citrullinemia type I (CTLN1) is a rare autosomal recessive disorder of the urea cycle caused by a deficiency in the argininosuccinate synthetase (ASS1) enzyme due to mutations in the ASS1 gene." (PMID 31208364, 2019). "Herein, we found that EVs derived from normal HLSCs have the potential to correct ASS1 enzyme deficiency in hepatocytes differentiated from HLSCs derived from a patient with citrullinemia type I, suggesting a potential application of EVs derived from stem cells in some inherited diseases." (PMID 28750687, 2017). "Citrullinemia type I disorders (CTLN1) is a genetic metabolic disease caused by argininosuccinate synthetase (ASS1) gene mutation." (PMID 39649700, 2024). "Preimplantation Genetic Testing (PGT) targeting likely pathogenic and pathogenic variants in the ASS1 gene, as rated by ACMG, allows the birth of healthy infants free from citrullinemia type 1." (PMID 39175751, 2024). "Type I citrullinemia (CTLN1, OMIM# 2,15,700) is caused by argininosuccinate synthase 1 gene (ASS1) mutations, while type II citrullinemia is caused by citrin gene (SLC25A13) mutations." (PMID 35309121, 2022). "In that regard, argininosuccinate synthetase 1 (ASS1), another component of the urea cycle that when defective causes citrullinemia type I (OMIM# 215700), is also expressed in several organs and cells of the immune system." (PMID 35711415, 2022). "Citrullinemia type I (CTLN1) is an inherited urea cycle disorder of the liver arising from a deficiency in the enzyme Argininosuccinate Synthase 1 (ASS1)." (PMID 31921856, 2019). "In the present study we demonstrated that EVs derived from normal HLSCs increased the production of urea and ASS1 enzymatic activity in hepatocytes differentiated from HLSCs derived from a patient with Citrullinemia type I." (PMID 28750687, 2017). "HLSCs were isolated from the liver of a patient with type I citrullinemia (ASS1-HLSCs) and characterized by fluorescence-activated cell sorting (FACS), immunofluorescence, and DNA sequencing analysis." (PMID 28750687, 2017). "The previous findings were discovered in a model of citrullinemia where mouse viability was rescued by gene transfer of the Ass1 to the liver." (PMID 29201027, 2017). "ASS1-HLSCs derived from the liver of a patient with citrullinemia type I were characterized to confirm their expression of stem cell markers similar to HLSCs." (PMID 28750687, 2017).
citrullinemia type I (continued). "For example, using established disease loci as a positive control, we highlight the examples of types I and II citrullinemia (MIM#215700, #603859), which are caused by mutations in ASS1 and SLC25A13, respectively." (PMID 27453504, 2016). "Citrullinemia type I (CTLN1) is caused by a deficiency or absence of the enzyme ASS1, resulting in increased intracranial pressure (ICP), increased neuromuscular tone, seizures, loss of consciousness, and death." (PMID 37601653, 2023). "Citrullinemia type I (CTLN1, MIM#215700) is a rare autosomal recessive disorder of the urea cycle caused by a defect in the function of argininosuccinate synthase resulting from mutations in the ASS1 gene." (PMID 37485339, 2023). "ASS1 encodes a protein that catalyses the penultimate step of the arginine biosynthetic pathway, mutations in which cause the life-threatening condition Citrullinemia, but has not, to our knowledge, been implicated in diseases of the musculoskeletal system." (PMID 35457215, 2022). "Citrullinemia type 1 (CTLN1) is an autosomal recessive urea cycle disorder caused by deficiency of the cytosolic enzyme argininosuccinate synthetase 1 (ASS1‐D; MIM #215700) due to pathogenic variants in the ASS1 gene located on chromosome 9q34.11." (PMID 31469252, 2019). "Of eight patients with Citrullinemia, seven were confirmed CTLN2 caused by mutations in SLC25A13 (MIM* 603859) gene, and only one cittrullinemia I (CTLN 1; MIM# 215700) caused by mutations in ASS1 (MIM* 603470) gene." (PMID 31737040, 2019). "Citrullinemia type I (CTLN1, MIM# 215700) is a rare autosomal recessive disorder of the urea cycle caused by a deficiency of the argininosuccinate synthetase (ASS, EC 6.3.4.5) enzyme due to mutations in the ASS1 gene." (PMID 31208364, 2019). "The aim of this study was to evaluate whether EVs derived from normal HLSCs restored ASS1 enzymatic activity and urea production in hepatocytes differentiated from HLSCs derived from a patient with type I citrullinemia." (PMID 28750687, 2017). "In this case study, we report the case of a 13-year-old girl with citrullinemia type 1 (MIM #215700), an autosomal recessive inherited disorder of the urea cycle, which was confirmed by the identification of a homozygous pathogenic variant in the argininosuccinate synthetase 1 (ASS1) gene." (PMID 38020658, 2023). "As some of these non-tumor diseases, such as citrullinemia type I (CTLN1), are caused by mutations in ASS1 gene or enzyme-defected splicing variants." (PMID 33859183, 2021). "The enzymatic activity of fibroblasts may be normal in children with citrullinemia or, conversely, have no enzymatic activity in asymptomatic patients; thus, sequencing of the ASS1 gene is recommended to confirm diagnosis and predict the prognosis of citrullinemia patients." (PMID 35433176, 2022).
hepatocellular carcinoma (43 papers, 2013 to 2026). A malignant tumor that arises from hepatocytes. "The pegylated arginine deiminase degrades arginine, creating arginine deficiency in ASS1-deficient cells and thereby inhibiting cancer cell growth, as demonstrated in melanoma and hepatocellular carcinoma cells in vitro." (PMID 41300990, 2025). "Another study demonstrated that ASS1 silencing in hepatocellular carcinoma cell lines is associated with simultaneous cisplatin resistance." (PMID 38053661, 2023). "Consistent with our studies, low ASS1 expression in tumor tissues is associated with poor prognosis of breast cancer and hepatocellular carcinoma patients." (PMID 33859183, 2021). "A recent publication on hepatocellular carcinoma showed that downregulation of ASS1 is associated with a more malignant cancerous phenotype and poor prognosis." (PMID 34818332, 2021). "Low ASS1 expression in tumor tissues is associated with poor prognosis of breast cancer and hepatocellular carcinoma patients." (PMID 33859183, 2021). "Contrary to our findings, worse patient survival for patients with ASS1 loss could be observed in other entities, for example, gastric cancer, hepatocellular carcinoma, or myxofibrosarcoma." (PMID 41300990, 2025). "Importantly, ASS1 loss has also been implicated in chemotherapeutic resistance in different tumors, including non-small cell lung cancer, ovarian cancer, and hepatocellular carcinoma, suggesting ASS1 to be a vulnerable metabolic hub for the development of therapy resistance." (PMID 40645971, 2025). "The suppression of ASS1 has been shown to enhance migration and invasion of hepatocellular carcinoma cells in vitro, while ASS1 overexpression inhibits metastasis in vivo." (PMID 41300990, 2025). "The upregulation of ASS1 in malignant THs contrasts with many other tumors (e.g., hepatocellular carcinoma or mesothelioma) that downregulate ASS1 and consequently become dependent on extracellular arginine." (PMID 38473304, 2024). "For hepatocellular carcinoma, according to the bioinformatics analysis, we and other researchers have found that the expression of ASS1 in LIHC is lower than the corresponding normal tissues." (PMID 38053661, 2023). "Intriguingly, the dual role of ASS1 has manifested in different cancer types; specifically, ASS1 is downregulated in breast cancer, hepatocellular carcinoma, etc.." (PMID 36978187, 2023). "One study showed that down-regulation of ASS1 due to DNA methylation was correlated with poor prognosis in hepatocellular carcinoma patients." (PMID 38053661, 2023). "The lower expression of ASS1 in tumor samples is related to the poor prognosis of patients with hepatocellular carcinoma (HCC)." (PMID 35674458, 2022). "Schematic diagram of NFIB promoting chemo-induced hepatocellular carcinoma by affecting urea cycle rate-limiting enzymes ASS1 and CPS1." (PMID 35655758, 2022). "In some tumors, such as glioblastoma, bladder cancer and hepatocellular carcinoma, methylation of the promoter region of the ASS1 gene mediates its silencing." (PMID 33859183, 2021). "After ASS1 knockdown using small interfering RNA (siRNA), the proliferation and invasion of Huh7 were enhanced, cyclin D1 was up-regulated, and anti-apoptotic protein bax was down-regulated, suggesting that ASS1 is a tumor suppressor gene in hepatocellular carcinoma." (PMID 38053661, 2023). "Our results demonstrated that ASS1 knockdown using siRNA promote the proliferation and invasion of Huh7, cyclin D1 was up-regulated, and bax was down-regulated, suggesting that ASS1 is a tumor suppressor gene in hepatocellular carcinoma." (PMID 38053661, 2023). "Stable silencing of ASS1 promoted the migration and invasion of hepatocellular carcinoma cells." (PMID 38053661, 2023). "Moreover, a correlation between reduced ASS1 protein levels and the ASS1 promoter methylation and resistance to cisplatin in hepatocellular carcinoma cell lines was reported." (PMID 27765932, 2016).
hepatocellular carcinoma (continued). "In hepatocellular carcinoma (HCC), the m6A‐modified circRAPGEF1 destabilizes ASS1 mRNA via competitive binding to IGF2BP3, driving aspartate metabolic reprogramming in liver cancer stem cells (LCSCs)." (PMID 40801445, 2025). "However, ASS1 might show different roles in hepatocellular carcinoma." (PMID 41460862, 2025). "During the transformation of hepatocytes into hepatoma cell, the regulatory effect of NFIB on ASS1 and CPS1 changed." (PMID 35655758, 2022). "We found that knockdown of NFIB can only augment the expression of CPS1 and ASS1 in normal hepatocyte but not in hepatoma cell, implying its stage-specific effect." (PMID 35655758, 2022). "A possible explanation is a secondary function of ASL, as it has been shown to influence cyclin A2 levels by direct binding in hepatocellular carcinoma, independent of its enzymatic activity within the ASS1-ASL node that also promoted anchorage-independent growth." (PMID 34535676, 2021). "ADI-PEG 20 has shown efficacy in liver cancer, particularly in hepatocellular carcinoma (HCC), due to the absence of ASS1 in cell lines." (PMID 37445845, 2023).
breast carcinoma (35 papers, 2014 to 2025). "Due to the deficiency of ASS1 in breast cancer, the ability of cancer cells to synthesize arginine decreases, causing these cells to become dependent on external arginine or to experience arginine starvation." (PMID 39973065, 2025). "Reduced arginine levels have been linked to mitochondrial dysfunction, primarily due to impaired oxidative phosphorylation (OXPHOS) and decreased ATP production in ASS1-deficient breast cancer." (PMID 40507936, 2025). "In breast cancer specifically, high ASS1 levels are associated with decreased survival, while ASS1 loss increases responsiveness to immune checkpoint blockade by reallocating aspartate toward pyrimidine synthesis and increasing mutational burden." (PMID 41511309, 2025). "Although ADI-PEG20 has shown promising efficacy in ASS1-deficient breast cancer cells, resistance to ADI in some ASS1-overexpressing breast cancer cell lines remains a challenge for ADI-based therapy." (PMID 39973065, 2025). "ADI-PEG20 induces extensive mitochondrial dysfunction in various ASS1-deficient breast cancer cell lines, subsequently inducing autophagy." (PMID 39973065, 2025). "They found that prolonged arginine starvation by exposure to ADI-PEG20 induced autophagy-dependent death of ASS1-deficient breast cancer cells along with a decrease in mitochondrial oxidative phosphorylation." (PMID 38053661, 2023). "A similar response to ADI-PEG20 with respect to ROS generation and mitochondrial dysfunction was reported in ASS1-deficient breast cancer cells." (PMID 33230565, 2021). "Dietary arginine restriction has also been shown to reduce tumor growth in a xenograft model of ASS1-deficient breast cancer." (PMID 31231467, 2019). "We analyzed metabolic footprint resulting from arginine starvation by exposure of ASS1-deficient MDA-MB-231 breast cancer cells to arginine free medium." (PMID 30393775, 2018). "However, in many cancer cells, including breast cancer, the transcription of ASS1 is suppressed, causing these cells to lose the ability to synthesize arginine." (PMID 39973065, 2025). "Association of low ASS1 expression with poor overall survival has been reported in multiple cancers, including bladder, myxofibrosarcoma, and breast cancer, although the number of breast cancer patients included was limited (n = 149) and all subtypes were analyzed." (PMID 40645971, 2025). "To evaluate an orthogonal dataset, we used the K–M Plotter dataset to analyze the correlation between ASS1 expression and OS of breast cancer patients who received endocrine therapy and observed that lower ASS1 expression was associated with worse OS (p = 0.022)." (PMID 40645971, 2025). "This suggests that breast cancer patients with ASS1 deficiency might be candidates for arginine starvation therapy." (PMID 39973065, 2025). "Additionally, in a breast cancer xenograft mouse model, dietary arginine restriction reduced the growth of ASS1-deficient breast cancer tumors in mice." (PMID 39973065, 2025). "Furthermore, dietary arginine restriction reduced tumor growth in a xenograft model of ASS1-deficient breast cancer." (PMID 30393775, 2018). "A study demonstrated hypoxia-induced ASS1 expression in ADI-PEG20 treated breast cancer cell lines in vitro, which may be associated with ADI resistance." (PMID 28750681, 2017). "With this tumor prosurvival role, EI24 and ASS1 both showed poor prognostic value in patients, not only in a same breast cancer dataset, but also across various cancer types." (PMID 40253325, 2025). "ASS1-expressing cells, such as the breast cancer cell line MDAMB468 or the osteosarcoma cell line MG63, did not respond in a meaningful way to dual treatment with ADI-PEG20 and A1331852." (PMID 39898973, 2025).